SHH (sonic hedgehog signaling molecule)
Diseases named in the same sentence as SHH in open-access papers (continued):
Sharing a sentence is not in itself a finding about the gene and the disease.
holoprosencephaly (82 papers, 2006 to 2025). Holoprosencephaly (HPE) is a complex brain malformation resulting from incomplete cleavage of the prosencephalon, occurring between the 18th and 28th day of gestation, and affecting both the forebrain and face, which results in neurological manifestations and facial anomalies of variable severity. "Third, while some progress has been made in understanding holoprosencephaly (HPE)—particularly through the identification of variants in genes such as SHH, SIX3, ZIC2, and TGIF1—most of these findings originate from non-Latin American cohorts." (PMID 40700109, 2025). "This developmental anomaly is reminiscent of that commonly observed in human holoprosencephaly, a disorder resulting from a deficiency in SHH activity." (PMID 38558491, 2024). "In human embryo, SHH is expressed in the notochord, the floorplate, the brain, and SHH mutations caused holoprosencephaly." (PMID 38093377, 2023). "Several SHH variants have further been identified as resulting in CAKUT; a nonsense mutation (c.388G>T) resulting in truncation at exon 2 of SHH caused renal hypoplasia along with holoprosencephaly and facial dimorphisms in a male patient." (PMID 37675356, 2023). "In humans, SHH dosage is critical for proper development, and loss of a single copy can result in the human condition holoprosencephaly." (PMID 37315133, 2023). "A female patient carrying the c.1061T>C missense mutation in exon 3 of SHH had renal hypoplasia, holoprosencephaly, cerebellar, and retinal defects." (PMID 37675356, 2023). "In humans, ZIC2 mutations are the second-most-common known cause (after SHH mutations) of the severe brain defect holoprosencephaly, in which the cerebral hemispheres fail to separate fully, owing to faulty midline specification." (PMID 36916392, 2023). "Among the novel variants found after NGS analysis, a novel variant p.H270Y in the SHH gene was identified in a patient presenting cyclopia with proboscis and cryptorchid." (PMID 35885957, 2022). "Insufficient expression of SHH during brain development results in holoprosencephaly, which can be caused by mutations either affecting the coding region of SHH or its regulatory landscape." (PMID 35377406, 2022). "Holoprosencephaly (HPE) is a typical example of a malformation associated with SHH gene deficiency, and severe cases of HPE have cyclopia." (PMID 35857502, 2022). "Mutations in human SHH gene cause holoprosencephaly (HPE), which is an autosomal dominantly inherited disorder." (PMID 35422684, 2022). "In humans, SHH variants are associated with holoprosencephaly (HPE), another developmental anomaly affecting the brain, and explain up to 37% of dominant HPE." (PMID 35885948, 2022). "One of the most common diseases associated with mutations in the SHH gene is a developmental malformation known as holoprosencephaly." (PMID 34298625, 2021). "The blockade of SHH by cyclopamine (an antagonist that binds SMO) also causes holoprosencephaly, which is evidence that SHH signalling is also involved." (PMID 34576017, 2021). "Genetic studies have found that although the normal parents and a child with holoprosencephaly share the same mutation, for instance in SHH, the child has additional mutations in another gene such as TGIF." (PMID 34576017, 2021). "Mutations in the sonic hedgehog (SHH) signaling gene CDON have been recently reported in patients with holoprosencephaly and with pituitary stalk interruption syndrome (PSIS)." (PMID 34235642, 2021). "In a large study of human patients, truncated mutations involving the N-terminus of SHH were shown to be more likely to cause holoprosencephaly than other types of mutations." (PMID 34576017, 2021). "In holoprosencephaly patients with SHH mutations, extra-neuroanatomical/related facial anomalies were rare, but cardiac and genitourinary anomalies were found in a small percentage of the patients, including those without frank holoprosencephaly." (PMID 34576017, 2021).
holoprosencephaly (continued). "The function of Sonic Hedgehog (SHH) signalling in human patients will be explored in the examples of holoprosencephaly caused by genetic mutations in SHH and short rib polydactyly (SRP), caused by abnormalities in primary cilia." (PMID 34576017, 2021). "The deletion of Gas1 in mice causes microform holoprosencephaly with partial loss of SHH signalling in target cells, but the additional loss of a single Shh allele in Gas1−/− mice caused a more severe phenotype, showing that GAS1 also interacts with SHH." (PMID 34576017, 2021). "This suggests that other factors apart from the canonical HH pathway are likely to be involved in holoprosencephaly malformation associated with SHH mutations." (PMID 34576017, 2021). "In humans, the loss of one SHH allele is sufficient to cause holoprosencephaly, whereas in shh−/− mice the loss of both alleles is needed to produce a similar phenotype." (PMID 34576017, 2021). "Holoprosencephaly appears to be determined by the mutation of the SHH gene, as reported by Bertolacini." (PMID 34814931, 2021). "Pathogenic variants in components of the SHH pathway have been described in patients with holoprosencephaly, isolated congenital hypopituitarism, and cranial/midline facial abnormalities." (PMID 32060556, 2020). "SHH mutations are commonly found in holoprosencephaly, a congenital syndrome that can be caused by aberrant Shh signaling." (PMID 29890674, 2018). "Although, mutations in the SHH pathway in humans are associated with various neurodevelopmental disorders, ranging from holoprosencephaly to schizophrenia, its expression pattern in the developing human brain is not well established." (PMID 29492654, 2018). "For example, an inversion of the SHH locus in a patient with features of a holoprosencephaly spectrum caused SHH to adopt a different limb enhancer in its new location, leading to its ectopic expression and subsequently causing various limb malformations." (PMID 26632825, 2015). "This deletion also included the SHH (sonic hedgehog) gene, which was associated with holoprosencephaly." (PMID 26294991, 2015). "For instance, midline Sonic hedgehog signaling is required for (i) and loss of SHH signaling causes holoprosencephaly, which in milder forms includes coloboma and microphthalmia." (PMID 24412933, 2014). "Previous studies indicated that mutations in human Sonic Hedgehog (SHH) caused holoprosencephaly, a developmental defect involving the forebrain and midface, which in severe cases includes anophthalmia and cyclopia." (PMID 25268479, 2014). "Loss of SHH expression or function in humans results in pathologies as diverse as holoprosencephaly, preaxial polydactyly or non-syndromic colobomatous microphthalmia." (PMID 24784881, 2014). "Mutation of human SHH or its downstream effectors result in a variety of severe developmental disorders; those affecting the head and face include holoprosencephaly, cyclopia and hypotelorism." (PMID 23555697, 2013). "In humans, mutations in SHH leads to solitary maedian maxilarry central incisor in addition to holoprosencephaly." (PMID 23566240, 2013). "Holoprosencephaly has also been associated with long-range regulator mutations leading to a haploinsufficiency of SIX3 or SHH proteins." (PMID 23284961, 2012). "As humans with loss-of-function mutations affecting the SHH pathway have holoprosencephaly, it is unsurprising that patients with isolated VACTERL association do not have SHH mutations." (PMID 21846383, 2011). "Mutations in the Sonic Hedgehog protein (SHH), for instance, result in holoprosencephaly, a condition whose behavioral and cognitive phenotype can be similar to ASD." (PMID 21740537, 2011). "If the phenotype of mutant SHH-associated holoprosencephaly were defined on narrowed thresholds, there would undoubtedly be pure cases of holoprosencephaly, with siblings showing the broader spectrum of holoprosencephalic features." (PMID 21740537, 2011).
holoprosencephaly (continued). "Mutations in SHH in humans cause holoprosencephaly [HPE3, OMIM 142945] and microphthalmia [OMIM 611638]." (PMID 19822228, 2010). "For SHH, human mutations so far described have resulted in holoprosencephaly and microphthalmia, but these have so far been mis-sense mutations or in-frame deletions." (PMID 19822228, 2010). "SHH is the major gene implicated in holoprosencephaly (12.7% of HPE cases: 50% of overall point mutations and 38% of overall large deletions)." (PMID 17274816, 2007). "SHH overexpression in zebrafish causes optic stalk hypertrophy and mutation of the human SHH gene is associated with holoprosencephaly and coloboma." (PMID 17173667, 2006). "In both humans and mice, mutations in SHH have been found to cause holoprosencephaly." (PMID 40034255, 2025). "In addition, mice deficient in the SHH gene have holoprosencephaly (smaller head) with cyclopia (single eye), and lack ventral cell types within the neural tube of the spinal cord and in most of the ribs; SHH-knockout mice die by 10.5 d." (PMID 36814325, 2023). "Among Hh family members, loss of sonic hedgehog (SHH) function results in pathologies as diverse as holoprosencephaly or preaxial polydactyly, whereas mutations in indian hedgehog (IHH) lead to bone growth defects (brachydactyly or acrocapitofemoral dysplasia)." (PMID 36230363, 2022). "SHH mutations were the first identified genetic causes of holoprosencephaly, but many other genes and environmental factors can cause malformations in the holoprosencephaly spectrum." (PMID 34576017, 2021). "Mutations in SHH are known to cause holoprosencephaly in humans." (PMID 34315464, 2021). "Mutations in SHH were the first genetic causes to be found in human holoprosencephaly and SHH mutations are one of the more common mutations in human patients with non-syndromic holoprosencephaly spectrum (." (PMID 34576017, 2021). "Mutations in SHH were the first genetic causes of human holoprosencephaly to be identified." (PMID 34884862, 2021). "Because of its key role in pattering the ventral forebrain, defects in the SHH pathway cause holoprosencephaly, the most common congenital disorder of the forebrain which is characterised by cyclopia, a failure to separate the forebrain into two lateral hemispheres, and craniofacial malformations." (PMID 29615599, 2016). "Holoprosencephaly is caused by disruption of genes contributing to the SHH-signaling pathway active in specifying rostroventral structures in the subpallium and results in selective loss of GABAergic cells characteristic of MGE derived interneurons in the neocortex." (PMID 24047602, 2015). "However, mutations within the key Hh-family member, Sonic Hedgehog (SHH) in humans can lead to the spectral disorder of Holoprosencephaly (HPE), often characterized by a variety of craniofacial defects including midline facial clefting and cyclopia." (PMID 19948063, 2009). "Mutations in SHH are the main cause of holoprosencephaly (HPE), a failure of the embryonic forebrain to separate into left and right hemispheres, and result in multiple midline defects including hypotelorism, cleft lip and palate, and hypopituitarism." (PMID 37794731, 2024). "Interestingly, mutations in SHH cause holoprosencephaly (OMIM# 142945), whose wide phenotypic spectrum also includes CL/P and the presence of a single median upper central incisor, which may be considered as a mild form of TA." (PMID 27699475, 2016). "These holoprosencephaly features were also found in human loss-of-function GLI2 mutations, but less severe compared to SHH mutations, which is reflected in the predictions of our neural tube closure model." (PMID 40034255, 2025). "Mice with a null mutation of Cdon, which encodes an SHH co-receptor, are sensitized to prenatal ethanol exposure to produce holoprosencephaly with defective expression of genes targeted by SHH." (PMID 35370658, 2022).
holoprosencephaly (continued). "Here, we address this issue by considering onset of cyclopia in sonic hedgehog (SHH)–inhibited chick embryos." (PMID 35857502, 2022). "Patients with SRP infrequently show mild brain malformations within the holoprosencephaly spectrum although canonical vertebrate SHH signalling is mediated in the primary cilium." (PMID 34576017, 2021). "Multiple mutations in HH co-receptors have been identified in human patients with holoprosencephaly, including in GAS1 in combination with SHH mutation and CDON which usually results in the microform type of holoprosencephaly." (PMID 34576017, 2021). "In line with a prominent role for SHH in forebrain development, defects in SHH signaling in humans and in mouse models result in midline formation defects, ultimately causing craniofacial malformation and holoprosencephaly (HPE)." (PMID 34698766, 2021). "The possible role of SHH will be considered using examples of holoprosencephaly and short-rib polydactyly (SRP) syndromes." (PMID 34576017, 2021). "Shh is one of the main genes altered in holoprosencephaly, SHH-haploinsufficiency being relatively frequent in patients." (PMID 33324176, 2020). "Holoprosencephaly and Currarino triad have been reported in terminal deletions; these conditions are attributed to the loss of MNX1 and SHH." (PMID 26064708, 2015). "Single allele mutations in the Hh pathway genes Sonic Hedgehog (SHH) and GLI2 cause holoprosencephaly with extremely variable phenotypic penetrance in humans." (PMID 24586787, 2014). "A similar phenomenon has also been observed in holoprosencephaly (MIM 142945), which can be caused by het-LOF mutations in SHH or by deletions or translocation BPs in a gene desert 5′ to the gene." (PMID 24363063, 2014). "These phenotypes mimic severe loss-of-function mutations within human SHH in HPE, which is characterized by facial anomalies including cyclopia, cleft lip, and underdeveloped jaw." (PMID 19948063, 2009). "The authors proposed that the phenotype was due to two position effect mutations, one at each breakpoint, altering the expression of the SHH (holoprosencephaly) and RUNX2 (CCD) genes." (PMID 18203189, 2008). "GLI2, SHH, and PTCH1 represent key hedgehog pathway members, which are critical for craniofacial patterning, and variations in these genes have been associated with holoprosencephaly with CL/P." (PMID 37745857, 2023). "Rare cases (about 5%) of severe SLO partients exhibit holoprosencephaly-like features without mutations in the main holoprosencephaly genes SHH, ZIC2, SIX3 and TGIF." (PMID 34576017, 2021). "Other genes associated with or independent of the SHH pathway, and chromosomal abnormalities (most frequently trisomy 13), have more recently been described as causing holoprosencephaly." (PMID 34884862, 2021). "A limitation of this study is the absence of analysis of the SHH gene, however this occurred due to the absence of holoprosencephaly, which was shown to be associated with the gene." (PMID 34814931, 2021). "Although there is the lack of SHH gene mutation and the absence of holoprosencephaly, the patient is affected by SMMCI with concomitant pan-hypopituitarism." (PMID 34814931, 2021). "They found that the usual mutations associated with human holoprosencephaly (SHH, TGIF, ZIC2 and SIX3) and GLI 3 were not present, and cholesterol studies were normal." (PMID 34576017, 2021). "This is unlike patients with SHH mutations who present with varying abnormalities in the holoprosencephaly spectrum." (PMID 34576017, 2021). "As many holoprosencephaly genes have not yet been found, and as clinical studies usually search for known gene mutations, it is possible that the changes in SHH-associated holoprosencephaly are actually due to mutations in more than one gene." (PMID 34576017, 2021).
holoprosencephaly (continued). "Indeed, mutations in signaling molecules (e.g., SHH and FGFs) and transcription factors (e.g., SIX3, SOX2, and SOX3) have been implicated in midline forebrain defects such as septo-optic dysplasia and holoprosencephaly." (PMID 33324176, 2020). "The significance of SHH in human brain development is illustrated by the dramatic consequences of SHH-pathway gene disruption, which include holoprosencephaly, seizure disorders, language or cognitive impairment, Down syndrome, hyperactivity, and schizophrenia." (PMID 29492654, 2018). "However, only mutations of HOXD13 and FOXF1 have been reported in humans with VACTERL association, while SHH and GLI2 mutations are associated with holoprosencephaly." (PMID 28003020, 2016). "Deletions SHH gene are known to be related to holoprosencephaly (OMIM ID: ∗600725)." (PMID 26064910, 2015). "Inherited or acquired modifications or abberations in components of the SHH cascade result in various phenotypes such as congenital anomalies (Pallister-Hall syndrome and holoprosencephaly) and various cancers including basal cell carcinoma and gastrointestinal cancers." (PMID 20015350, 2009). "Decreased SHH signaling (either through haploinsufficiency for SHH or by increasing the repressive activity of PTCH1) has severe developmental consequences that mirror human holoprosencephaly (HPE), a common forebrain defect resulting from the failure of the cerebral hemispheres to separate." (PMID 26935104, 2016). "On the other hand, the relatively mild abnormalities observed in optical disc and the absence of holoprosencephaly in the patient are in stark contrast with the severe craniofacial defect and abnormal forebrain development found in patients with SHH loss of function." (PMID 24784881, 2014). "Genetic dysfunctions of SHH (responsible for ventral patterning) and BMP (involved in dorsal patterning), either directly or indirectly, tend to result in holoprosencephaly." (PMID 24368961, 2013). "In contrast, the complete absence of SMO or SHH in mouse models resulted in holoprosencephaly because SHH is required for cell migration and axonal guidance in the developing brain." (PMID 34576017, 2021). "Human SHH gene is responsible for severe developmental conditions like holoprosencephaly, and there are no evidences of SHH allelism, that may lead to milder phenotype." (PMID 28390009, 2017). "Moreover, an abnormal lack of SHH diffusion from the Shh-expressing preoptic subarea postulated as a subpallial organizer (Puelles, 2017), needs to be considered to understand any subpallial anomalies present in holoprosencephaly." (PMID 33324176, 2020). "Although the association of LSS mutations and holoprosencephaly was not proven by pedigree analysis in a previous study, some patients with LSS mutations, including our patients, have midline anomalies or growth failure, which are observed in diseases of cholesterol metabolism or SHH signaling." (PMID 32101538, 2020).